RIMBP3 (RIMS binding protein 3)
Description:
Probable component of the manchette, a microtubule-based structure which plays a key role in sperm head morphogenesis during late stages of sperm development.
Synonyms: RIM-BP3.A; RIM-BP3.1; KIAA1666; RIMBP3A; RIMBP3.1; RIM-BP3
Tractability: PROTAC: ubiquitination databases record sites on it.
Gene: Protein-coding gene on chromosome 22 (18,605,815 to 18,611,919, reverse strand). Ensembl gene ENSG00000275793.
Subcellular location: Cytoplasm, cytoskeleton
Subcellular location (Human Protein Atlas): Plasma membrane; Vesicles
Gene Ontology:
Molecular function: protein binding; benzodiazepine receptor binding
Biological process: fertilization; neuromuscular synaptic transmission; spermatid development
Cellular component: manchette; nucleus; cytoskeleton
Genetic constraint (gnomAD): Loss-of-function variants: 1 observed, 29.5 expected, observed/expected ratio (o/e) 0.0339, 90% interval 0.011 to 0.16. The synonymous counts are far from expectation, so gnomAD's model fits this gene poorly and the ratio says little. Missense variants: 21 observed, 503.35 expected, observed/expected ratio (o/e) 0.0417, 90% interval 0.029 to 0.06. Synonymous variants: 8 observed, 189.64 expected, observed/expected ratio (o/e) 0.0422, 90% interval 0.024 to 0.076.
Homologues: Orthologues: rat Rimbp3 (64% identical), mouse Rimbp3 (63% identical), Drosophila melanogaster Rbp (14% identical), Caenorhabditis elegans rimb-1 (13% identical). Paralogues in human: RIMBP3B (99% identical), RIMBP3C (99% identical), TSPOAP1 (29% identical), RIMBP2 (16% identical).
Diseases named in the same sentence as RIMBP3 in open-access papers:
RIMBP3 is named in the same sentence as 7 diseases in open-access papers, as found by Europe PMC text mining. Sharing a sentence is not in itself a finding about the gene and the disease.
RIMBP3 shares sentences with these, for which no sentence is quoted: Ataxia (1 paper); cancer (1); kidney stone (1); male fertility (1); male infertility (1); oligospermia (1); Parkinson disease (1).